AXL (AXL receptor tyrosine kinase)
Diseases named in the same sentence as AXL in open-access papers (continued):
Sharing a sentence is not in itself a finding about the gene and the disease.
osteosarcoma (continued). "In an phase II trial of the AXL inhibitor cabozantinib in osteosarcoma, the 6-months PFS rate was 33%, the median PFS was 6.2 months, and the PR rate was 12%." (PMID 32984034, 2020). "Linc00852 increased AXL expression and promoted the progression of osteosarcoma through the AXL‐AKT pathway." (PMID 32673448, 2020). "Osteosarcoma cell‐derived exosomes with high or low AXL expression were isolated from the conditioned medium of 143B and HOS cells, which were sorted and recovered by flow cytometry." (PMID 32673448, 2020). "A retrospective study showed that one in five patients with osteosarcoma treated with an AXL inhibitor, sunitinib, showed PR." (PMID 32984034, 2020). "There have been identified AXL as one of the specific RTKs that can activated and promote the phenotype of osteosarcoma cells in vitro." (PMID 32984034, 2020). "The results suggested that there existed a competing endogenous RNAs (ceRNA) regulatory network among linc00852, AXL mRNA, and miR‐7‐5p in osteosarcoma cells." (PMID 32673448, 2020). "Nevertheless, the roles of lncRNAs transferred by exosomes between different AXL levels in osteosarcoma are poorly understood." (PMID 32673448, 2020). "On the other hand, elevated AXL expression correlated with increased adherence, motility, and invasiveness of osteosarcoma cell lines." (PMID 31694201, 2019). "GAS6 and related AXL receptor tyrosine kinase have been shown to be involved in metastasis of renal cancer and osteosarcoma." (PMID 26954680, 2016). "High AXL expression predicts a poor outcome in patients with myxoid liposarcoma and activated AXL was an independent predictor of a worse prognosis in osteosarcoma patients." (PMID 25528764, 2014). "Accordingly, in osteosarcoma and triple-negative BC cell lines, AXL-signaling pathway interference had considerably greater effects on migration than on proliferation in vitro." (PMID 25528764, 2014). "Taken together, NRlncRNA SNHG6 may be of great significance in osteosarcoma cell necroptosis through SNHG6/AXL/AKT signaling axis." (PMID 38194709, 2024). "Finally, other studies have found that osteosarcoma cells highly express AXL, of which the inhibition significantly reduces lung metastases." (PMID 36980534, 2023). "The available literature indicates the role of AXL as a mediator of osteosarcoma metastasis." (PMID 38203403, 2023). "Moreover, the knockdown of AXL in a human osteosarcoma cell line induced apoptosis by increasing poly (ADP-ribose) polymerase 1 (PARP) expression and inhibited proliferation via AKT signaling." (PMID 38203403, 2023). "In addition, It was found that AXL regulates the proliferation, cycle, migration, and differentiation of osteoblasts and osteoclasts in osteosarcoma." (PMID 36408274, 2022). "A positive feedback loop between exosome derived linc00852 and AXL demonstrated that exosome derived linc00852 may act a novel osteosarcoma biomarker." (PMID 34712664, 2021). "Knockdown of AXL in osteosarcoma cells leads to decreased proliferation and increased apoptosis." (PMID 32984034, 2020). "In our study, we proved that the donor osteosarcoma cells with high AXL expression could transfer the exosomal linc00852 to the receiver cells with low AXL and increase the abilities of proliferation, migration, and invasion of the receiver cells." (PMID 32673448, 2020). "In this study, we investigated the contributions of lncRNA transferred by exosomes from donor cells with high AXL expression to receiver cells with low AXL during the process of the invasion and metastasis of osteosarcoma, and attempted to reveal the mechanisms." (PMID 32673448, 2020). "Exosomal linc00852 promotes osteosarcoma migration and invasion by upregulating AXL." (PMID 32673448, 2020).
osteosarcoma (continued). "In this study, we found that exosomes, which emerged as novel cell‐cell communication mediators, were transferred from donor cells with high AXL expression to receiver cells with low AXL expression in osteosarcoma to carry the regulative message in the progression of the tumor." (PMID 32673448, 2020). "With the understanding of exosomes, we hypothesized that exosomes would be the important secreted factor in the communication between the two groups with high and low AXL expression in osteosarcoma." (PMID 32673448, 2020). "We also illustrated that overexpression of linc00852 was positively associated with AXL mRNA and showed a negative relationship with miR‐7‐5p, which strongly revealed that a regulatory network existed between these three factors in osteosarcoma." (PMID 32673448, 2020). "We had demonstrated that osteosarcoma could be divided into two tumor groups with different probabilities of invasion and metastasis according to the expression level of AXL." (PMID 32673448, 2020). "In addition, miR-199a-3p and lncRNA DANCR regulate the progression of osteosarcoma through targeting AXL." (PMID 32984034, 2020). "Thus, we demonstrated a positive feedback loop that regulates exosomal linc00852 and AXL in osteosarcoma." (PMID 32673448, 2020). "Increased expression of linc00852 caused AXL and AKT overexpression, indicating that linc00852 could promote the progression of osteosarcoma cells through the AXL‐AKT pathway." (PMID 32673448, 2020). "Jiang N revealed that DANCR could enhance tumor progression and cancer stemness features in osteosarcoma by upregulating AXL via miR-33a-5p inhibition." (PMID 29753317, 2018). "Furthermore, a review of the literature suggests that KIT, PDGFRs, MET, IGF‐1R, and AXL could also serve as potential therapeutic targets for osteosarcoma." (PMID 40344484, 2025). "Therefore, SNHG6 may regulate the proliferation, migration, and invasion of osteosarcoma cells through AXL." (PMID 38194709, 2024). "In addition, we reviewed the literature and found that MET, IGF-1R, and AXL may also be relevant targets for the treatment of osteosarcoma." (PMID 32984034, 2020). "In conclusion, our study demonstrated that osteosarcoma cells with high AXL expression promoted growth, invasion and metastasis of the other tumor cells with low AXL expression through releasing linc00852‐containing exosomes and a positive feedback regulation loop between AXL and exosomal linc00852." (PMID 32673448, 2020). "In osteosarcoma cell-lines (like 143B and MG-63), it is observed that LINC00852 acts as a transcription factor and increase the expression of AXL gene." (PMID 40491847, 2025). "In osteosarcoma cell lines, DANCR up-regulated the expression of kinase AXL by acting as a sponge of miR-33a, leading to cell proliferation, migration, and metastasis." (PMID 38968577, 2024). "For example, SRC kinase, which plays a key role in the development of osteosarcoma, can be activated, respectively by VEGFRs, KIT, RET, PDGFRs, IGF-1R, and AXL." (PMID 32984034, 2020). "We propose that the miR-509-3p/AXL and miR-509-3p/ARHGAP1 axes have the potential to uncover new druggable targets for the treatment of drug resistant metastatic osteosarcoma." (PMID 31836741, 2019). "In osteosarcoma cells, GAS6-induced AXL activation protected serum starved cancer cells from apoptosis, whereas knockdown of AXL inhibited cell proliferation and increased apoptosis." (PMID 31694201, 2019). "Additionally, we demonstrated that NRlncRNA SNHG6 regulated AXL and AKT signaling in osteosarcoma cells and the proliferation, migration, and invasion of tumor cells." (PMID 38194709, 2024). "A study using tissue microarray from human osteosarcoma samples reported increased AXL expression compared with corresponding adjacent non-cancerous tissue." (PMID 38203403, 2023).
osteosarcoma (continued). "Increased phosphorylation of AXL has been described to be correlated with strong expression of MMP-9, a metalloprotease modulating the metastatic cascade, as well as with recurrence of lung metastasis in osteosarcoma patients." (PMID 38203403, 2023). "At present, there is no report about the efficacy of single-target drugs against AXL in osteosarcoma." (PMID 32984034, 2020). "Furthermore, we showed that TAS‐115 inhibited the phosphorylation of PDGFRα, AXL, and FLT‐3 and decreased cell proliferation in LM8 and other human osteosarcoma cell lines." (PMID 32128992, 2020). "The receptor tyrosine kinases (RTKs) MET, IGF-1R, AXL, PDGFRs, KIT, and FGFRs might be relevant but unimportant targets for osteosarcoma treatment." (PMID 32984034, 2020). "The receptors MET, IGF-1R, AXL, PDGFRs, KIT, and FGFRs might be relevant but unimportant RTKs for osteosarcoma." (PMID 32984034, 2020). "To investigate the expression of AXL on sarcoma cells, we collected a panel of seven human cell lines, including CAL-72 (osteosarcoma), ESS-I (endometrial stromal sarcoma), HT-1080 (fibrosarcoma), SAOS-2 (osteosarcoma), Rh-30 (rhabdomyosarcoma), SW982 (synovial sarcoma) and RD-ES (Ewing’s sarcoma)." (PMID 36980534, 2023). "In human osteosarcoma cells, DANCR could upregulate AXL expression via miR-33a-5p inhibition." (PMID 29416741, 2018).
lung adenocarcinoma (24 papers, 2014 to 2025). A carcinoma that arises from the lung and is characterized by the presence of malignant glandular epithelial cells. "AXL expression displays a positive correlation with PD-L1 expression in lung adenocarcinoma with epidermal growth factor receptor (EGFR) mutation, and abolition of AXL kinase activity inhibits PD-L1 mRNA expression in a lung adenocarcinoma cell line with EGFR mutation." (PMID 32403421, 2020). "AXL drives MIG6 expression to downregulate EGFR in lung adenocarcinoma cells, suggesting MIG6’s pivotal role in orchestrating this switch." (PMID 37834326, 2023). "The combination treatment with FO and Se suppresses AXL expression in HCC827 lung adenocarcinoma cells, although few studies show either FO or Se modulates AXL/Gas6 expression in cancer cells." (PMID 36547898, 2022). "When AXL is suppressed, the level of PD-L1 is decreased in lung adenocarcinoma and human triple-negative breast cancer cell lines." (PMID 34778071, 2021). "This interaction is also demonstrated in lung adenocarcinoma, which showed that AXL expression significantly correlated with the expression of genes encoding PD-L1 and CXC chemokine receptor 6 (CXCR6)." (PMID 34778071, 2021). "AXL expression correlated with PD-L1 expression in lung adenocarcinomas and AXL targeting significantly reduced PD-L1 gene expression in the tumor cells." (PMID 31694201, 2019). "In lung adenocarcinoma, recent studies have confirmed that AXL inhibition decreased the expression of PD-L1 and CXC chemokine receptor 6 (CXCR6), especially when EGFR was mutated." (PMID 31703465, 2019). "Recent studies demonstrate overexpression of the receptor tyrosine kinase AXL in lung adenocarcinoma tumor tissues compared with adjacent lung tissues and strong association of AXL expression with tumor invasiveness." (PMID 29731983, 2018). "In this study, we analyzed clinical, pathological, and molecular features of AXL expression in lung adenocarcinomas (LADs)." (PMID 27100677, 2016). "In addition, a study using liquid biopsies for informative diagnosis in lung adenocarcinoma patients found AXL to be more highly expressed in circulating tumor cells from patients with a poor prognosis." (PMID 35158733, 2022). "Endocytosis of NE by the lung adenocarcinoma cells caused upregulation of PI3K-AKT survival signalling, whereas in PCa, extracellular NE triggered ERK signaling via the combined activation of receptor tyrosine kinases AXL and EGF." (PMID 35874783, 2022). "Lung adenocarcinomas with strong AXL expression may be characterized by mesenchymal status, higher expression of CSC markers, and frequent presence of driver gene mutations." (PMID 27100677, 2016). "Compared to normal lung tissue, YAP1 was shown overexpressed in lung adenocarcinomas, and knockdown of YAP1 markedly downregulated the expression of AXL and inhibited the proliferation and invasion of lung adenocarcinomas suggesting that AXL is a mediator of the oncogenic function of YAP1." (PMID 25337673, 2014). "Furthermore, AXL and its ligand Gas6 were similarly observed to be upregulated along with vimentin upregulation and E-cadherin loss in the COR cell clones resistant to the EGFR T790M-targeting drug, CO-1686 in EGFR-mutated lung adenocarcinoma." (PMID 25337673, 2014). "Activated TAZ in lung adenocarcinoma cells elicits the expression of a panel of target genes that promote brain metastasis, including ABL2, AXL, and L1CAM." (PMID 37835395, 2023). "This combined treatment also decreased the AXL levels and gefitinib resistance in EGFR-mutant HCC827 lung adenocarcinoma cells, thereby increasing apoptosis, suppressing the EMT, and eliminating cancer-cell stemness." (PMID 36547898, 2022). "We recently reported the prognostic significance of the co-expression of AXL and its ligand, GAS6, in lung adenocarcinoma." (PMID 29930762, 2018).
lung adenocarcinoma (continued). "In lung adenocarcinoma, overexpression of miR-432 inhibited cell proliferation through arresting cell cycle by regulation of two directly targets E2F3 and AXL." (PMID 28947999, 2017). "Similarly, in lung adenocarcinoma, miR-432 functioned as a tumor suppressor gene through targeting E2F3 and AXL." (PMID 28947999, 2017). "In other cancer types, AXL can upregulate immune checkpoint proteins and alter chemokine signaling in lung adenocarcinoma, suggesting therapies that target immune checkpoint molecules like anti-PDL1 might be ineffective unless a combination therapy is used which also targets AXL." (PMID 32148495, 2020).
colon carcinoma (20 papers, 2013 to 2024). "We demonstrated that TAM receptors are O‐glycosylated and GALNT2 promotes invasive behaviors of colon cancer cells partly through modification of O‐glycosylation and protein stability of AXL." (PMID 36409270, 2023). "GALNT2 can modify O‐glycans on AXL to increase AXL protein levels and in turn promote colon cancer cell invasiveness." (PMID 36409270, 2023). "Taken together, these results suggest that AXL is involved in GALNT2‐promoted invasiveness in colon cancer cells." (PMID 36409270, 2023). "Collectively, our data demonstrated that GALNT2 can generate O‐glycans on AXL and regulate AXL protein levels in colon cancer cells." (PMID 36409270, 2023). "The administration of AXL inhibitors in orthotopic colon cancer models using HCT116 tumor cells resulted in significant inhibition of tumor growth and peritoneal metastatic dissemination." (PMID 33759958, 2021). "A recent study demonstrated the paradoxical effect of AXL and the receptor tyrosine kinase Mer in colon cancer." (PMID 33759958, 2021). "Results of the real-time PCR showed that inhibition of PODXL-downregulated TAZ downstream targets including AXL, CTGF, CYR61, Survivin, and CyclinD1, confirming the association between PODXL and the TAZ signature in colon cancer patients." (PMID 28946619, 2017). "Moreover, the GALNT2‐mediated invasion of colon cancer cells was almost blocked by AXL inhibitors or siRNAs, suggesting that AXL is a crucial determinant in the GALNT2‐mediated invasiveness." (PMID 36409270, 2023). "Therefore, it is highly possible that other GALNT enzymes can also glycosylate AXL in colon cancer cells." (PMID 36409270, 2023). "Interestingly, AXL expression was upregulated by Long non-coding RNA (lncRNA) CALIC in complex with RNA-binding protein hnRNP-L in colon cancer cells, while knockdown of either CALIC or AXL inhibited metastases in vivo." (PMID 37469409, 2023). "Indeed, in colon cancers analyzed, CpG islands resulted partially methylated in cells with low AXL expression, as compared to cells with the highest AXL levels." (PMID 33182542, 2020). "In the present study, we have shown that TAZ mRNA expression is positively correlated with two of its downstream targets, AXL and CTGF, and that TAZ is significantly associated with poor survival of colon cancer patients in two independent colon cancer datasets, comprising 522 patients." (PMID 23372686, 2013). "Thus, AXL could represent a novel molecular marker for advanced staged mesenchymal-like colon tumors." (PMID 33570712, 2021). "For example, treatment with AXL inhibitor S49076 markedly decreased tumor resistance to bevacizumab, a VEGF/VEGFR blocker, in a colon carcinoma xenograft model and attenuated colony formation of FGFR1/2- and AXL-positive hepatocarcinoma cells." (PMID 37469409, 2023). "When colon cancer cells were transfected with siRNA targeting TYRO3, AXL, MER, or NC, it was found that the cleaved form of poly (ADP-ribose) polymerase (PARP) and caspase 3 were significantly increased." (PMID 34721022, 2021). "When crystal violet staining was performed after down-regulating TAM RTKs in colon cancer cells, we found that the number of cells in the TYRO3-downregulated group was significantly reduced compared to the MER- and AXL-downregulated groups." (PMID 34721022, 2021). "To investigate the effect of siRNA targeting TYRO3, AXL and MER on signaling pathways, we analyzed the signaling pathways involved in cell proliferation by western blot analysis in colon cancer cells." (PMID 34721022, 2021). "AXL and CTGF were found, when combined with TAZ mRNA expression, to form a better prognostication in these two independent colon cancer patient databases." (PMID 26805820, 2016). "In two independent colon cancer databases, TAZ-TEAD complexes inducing the upregulation of AXL and CTGF have been identified." (PMID 26805820, 2016).